PROM1 (prominin 1)
Diseases named in the same sentence as PROM1 in open-access papers (continued):
Sharing a sentence is not in itself a finding about the gene and the disease.
adenocarcinoma (43 papers, 2008 to 2025). A common cancer characterized by the presence of malignant glandular cells. "We showed previously that Prominin1 (PROM1) marks basal stem cells in gastric antral glands and that their lineage forms adenocarcinomas in Prom1CreERT2/LacZ;KrasG12D;Trp53Flx/Flx (P1KP) mice." (PMID 36175792, 2022). "Indeed, extensive expression of prominin-1 in epithelial cancer cells was demonstrated in a murine model of chronic intestinal inflammation that develops spontaneously adenocarcinomas." (PMID 24911657, 2014). "For this, two specimens of adenocarcinomas arising in the background of BE were assessed for the expression of CDX2, OLFM4, EPHB2, and PROM1 by qRT-PCR analysis." (PMID 25996368, 2015).
infection (37 papers, 2011 to 2026). The state of being infected such as from the introduction of a foreign agent such as serum, vaccine, antigenic substance or organism. "The concomitant elongation of distal cilia suggests that disruption of the Notch–PROM1 regulatory axis contributes to infection-induced remodeling of the multiciliated epithelium." (PMID 41571441, 2026). "Therefore, the results indicate that the CLEC7A and PROM1 genes are causal genes affected by rs11053595 and rs62290169 SNPs, respectively, whose allelic variations result in disturbances of the cytokine production influencing the innate immune response towards infection caused by P. brasiliensis." (PMID 37108883, 2023). "Moreover, gene ontology (GO) analysis revealed that pathways related to responses to infection or to phototransduction were up- and downregulated, respectively, in the Prom1-KO retina at P21, suggesting that Prom1 plays key roles in retinal homeostasis." (PMID 34664634, 2021). "At 24 h post-infection with either Wuhan or Omicron strains, the levels of AXL and PROM1 were unaffected." (PMID 40659811, 2025). "We found several apoptotic cells in the Prom1−/− retina upon infection with control AAV-Gfp (I′), which was never detected in the Prom1+/− retina (H′) under the same experimental conditions; however, infection with AAV-Igf1 significantly decreased the number of TUNEL-positive cells (J′)." (PMID 38252153, 2024).
retinal disorder (15 papers, 2014 to 2026). Any disease or disorder of the retina. "Prom1-related retinopathies are associated with various pathogenic Prom1 variants and heterogeneous phenotypical characteristics." (PMID 39513868, 2024). "In conclusion, our findings suggest that the entity, previously known as CORD7, corresponds in fact to PROM1-retinopathy, and is consequent upon the missense pathogenic variant p.Arg373Cys." (PMID 35947379, 2022). "PROM1 mutations cause various human retinal disorders by disrupting the cilium‐derived photoreceptor outer segment, a phenomenon phenocopied in Prom1 null mice." (PMID 30523147, 2019). "PROM1 mutations, including p.R373C, p.Q576X, p.G614fsX626, and p.Y452fsX12, were associated with a heterogeneous group of inherited retinal disorders with autosomal recessive and dominant inheritance patterns." (PMID 24484648, 2014). "These disorders include retinal disorders linked to variants in prominin-1 (PROM1)." (PMID 39355864, 2024). "In addition to an autosomal recessive PROM1 early-childhood-onset retinopathy, an autosomal dominant later-onset macular retinal phenotype has been documented in some individuals heterozygous for PROM1 mutations, including in our study." (PMID 29416601, 2018). "Genes such as PRPH2 and PROM1 caused five and four different types of retinopathies, respectively, with predominant autosomal dominant traits for the PRPH2 gene and autosomal recessive traits for the PROM1 gene." (PMID 30374144, 2018). "There are 27 carriers of the PROM1 variant within the Moorfields patient database, and the phenotype of the CORD7 affected individuals is in keeping with the variable macular/CORD disease seen in other PROM1-retinopathy cases." (PMID 35947379, 2022). "Review of clinical data of age-matched PROM1-retinopathy cases and the CORD7 affected family members showed striking similarities and a phenotype entirely consistent with PROM1-retinopathy in the CORD7 family." (PMID 35947379, 2022). "Also, RP1L1, PROM1, CRX, CFI and CFB, and KCNJ13 have been linked to retinopathy." (PMID 33330132, 2020).
gastrointestinal tumors (6 papers, 2013 to 2020). "As well known, one of the sorting markers frequently used in the separation/enrichment to these cancerous cells with stemness characteristics in gastrointestinal neoplasm is the cell surface protein nominated as CD133/prominin-1." (PMID 24653835, 2014).
degenerative diseases (4 papers, 2013 to 2024). "Thus a thorough documentation of prominin-1 expression becomes a crucial matter not only for understanding biological details of brain development, but also to establish potential stem cell-based treatments for neurodegenerative diseases." (PMID 23723983, 2013).
genetic disorders (2 papers, 2020 to 2023). "Mutations in PROM1 were mainly missense and truncating mutations, including p.R373C, p.Y452fsX12, p.G614fsX626, and p.Q576X in the prominin domain, which are associated with human inherited diseases." (PMID 31164716, 2020).
inflammation (2 papers, 2011 to 2019). Aberrant reaction of the microcirculation characterized by movement of fluid and leukocytes from the blood into extravascular tissues. "Next, we addressed the differentiation potential of prominin-1+ progenitors during acute pulmonary inflammation." (PMID 21943210, 2011). "Injection of prominin-1+/EGFP+ cells 2h after bleomycin instillation protected from pulmonary inflammation and fibrosis at day 7 (not shown;)." (PMID 21943210, 2011).
connective tissue disease (1 paper, 2018). "IPA demonstrated the involvement of relevant genes (OPN, POSTN, MMP-1, MMP-7, Prominin-1, and others) in the network “connective tissue disease, organismal injury and abnormality”, and other functions related to cell movement and connective tissue disorder." (PMID 30111332, 2018).
PROM1 also shares sentences with these, for which no sentence is quoted: lymph node metastasis (37 papers); ovarian tumors (33); cholangiocarcinoma (32); cervical carcinoma (21); metastatic tumors (20); myocardial infarction (19); head and neck squamous cell carcinoma (18); colon adenocarcinoma (17); malignant glioma (17); colorectal adenocarcinoma (16); acute myeloid leukemia (14); Ewing sarcoma (14); hepatoblastoma (14); ischemic heart disease (14); oral squamous cell carcinoma (14); pancreatic adenocarcinoma (13); small cell lung carcinoma (13); rectal cancer (12); colorectal (10); laryngeal carcinoma (10); clear cell renal cell carcinoma (9); liver cirrhosis (9); rhabdomyosarcoma (9); endometrial tumors (8); ependymoma (8); hemangioma (8); lymphoma (8); type 2 diabetes (8); gallbladder carcinoma (7); myocardial ischemia (7).
A further 323 diseases each share a sentence with PROM1 in 6 papers or fewer.